TTF1 (transcription termination factor 1)
Diseases named in the same sentence as TTF1 in open-access papers (continued):
Sharing a sentence is not in itself a finding about the gene and the disease.
tumor (continued). "Next, immunohistochemical (IHC) staining was performed using cytokeratin 7 (CK7), cytokeratin 20 (CK20), and thyroid transcription factor-1 (TTF-1), in order to clarify the origin of the tumor." (PMID 27714647, 2016). "The expression of TTF-1 was localized in the nucleus of tumor cells and in normal alveolar epithelial cells; therefore, the stainability of the latter was used as an internal control." (PMID 25733373, 2015). "The histologic appearance of the tumor was suggestive of metastatic thyroid carcinoma, which we were able to confirm using IHC for thyroglobulin and TTF-1." (PMID 26550511, 2015). "The immunohistochemistry of resected specimens exhibited tumor cells that were TTF-1 positive in 89% of cases and CK7+/CK20−/CDX2− in all cases." (PMID 26425638, 2015). "In conclusion, our study confirmed that the majority of SCLCs were of the peripheral type, that the tumor location significantly correlated with TTF-1 expression and that the location was a significant prognostic factor." (PMID 26705222, 2015). "We examined patient survival using the Kaplan–Meier method to explore potential correlations between tumor location and TTF-1 expression." (PMID 26705222, 2015). "Nuclear TTF-1 expression in tumor cells was observed in 164 of 247 (66.4%) ACs and SCCs, including 161 of 198 (81.3%) ACs and 3 of 49 (6.1%) SCCs." (PMID 25733373, 2015). "The present study clearly demonstrated that 74% of SCLCs arise in the peripheral lung and TTF-1 expression significantly correlated with peripheral location of the primary tumor." (PMID 26705222, 2015). "TTF-1 expression significantly correlated with peripheral location of the primary tumor (P = 0.030, chi-square test)." (PMID 26705222, 2015). "On immunohistochemical studies (IHC), tumor cells were positive for calcitonin, TTF-1, and thyroglobulin thus confirming the primary site to be thyroid and the tumor." (PMID 25478248, 2014). "The tumor tissues were further confirmed by immunohistochemical assessments, which showed that thyroid transcription factor 1 (TTF-1 or NKX2–1) and Cytokeratin 7 (CK7) were all significant positive." (PMID 25474437, 2014). "RT-PCR analysis further confirmed that both the primary tumor and CTCs demonstrated TTF-1 expression." (PMID 25474037, 2014). "It has become apparent that TTF-1 expression has biological and clinical functions in the opposite direction that act in tumor progression." (PMID 24949691, 2014). "Immunohistochemical staining showed CDX-2(−), CK20(+), CK7(−) and TTF-1(−) in the tumor cells, confirming metastasis from colorectal adenocarcinoma." (PMID 24348839, 2014). "In each case, there was clinical or radiological confirmation of a primary thyroid malignancy, and all these tumours demonstrated positive immunoreactivity to TTF-1 and Tg." (PMID 23533895, 2013). "As novel observations, we here find significantly more TTF-1 positive tumors with increased tumor cell proliferation (Ki67), a basal like phenotype (CK5/6 and/or P-cadherin expression), lymph node metastasis, ER negativity, and blood vessel invasion." (PMID 23675755, 2013). "After 4 weeks, all mice (n=8) had developed a large solid mass at the site of BHP18-21v (TTF1) cell injection, and the mean of the maximum tumor diameter was 25±5.5 mm." (PMID 24014739, 2013). "As a result, a novel aspect of TTF-1 is that losing expression of TTF-1 made tumor cells generating EMT and then resulting in the worse prognosis of patients." (PMID 23706092, 2013). "The results support previous findings that TTF-1 controlled differentiation of tumor and limited metastatic potential in a mouse model." (PMID 22940844, 2012). "Tumor samples from eighteen patients with papillary TC (PTC), who underwent total thyroidectomy at an age of ≤21, were screened for TTF-1 and TTF-2 variants." (PMID 22481925, 2012).
tumor (continued). "For example, if the tumor expresses thyroid transcription factor-1 (TTF-1) this is strong evidence that the tumor is a pulmonary primary." (PMID 23119210, 2012). "Immunostains performed on consecutive serial histological sections showed that both TCF-4 and TTF-1 are expressed in the same areas within tumours." (PMID 21814573, 2011). "It is remarkable the positivity of epithelial cells for TTF-1, which suggest that the tumour has a certain pneumocytic differentiation." (PMID 21798017, 2011). "Staining patterns of TTF-1 in combination with multiple cytokeratin marker positivity further allows deduction of primary tumor location and even levels of differentiation of such metastatic tumor cells." (PMID 26316932, 2011). "The presence of pale round cells in tumor and immuno-positivity of round cells for TTF-1, EMA and ER, PR support the diagnosis of PSH." (PMID 21599956, 2011). "TTF-1 expression in SCCB was found in 40% of the tumours in 2 studies, demonstrating that this marker can be expressed in SCC other than those of pulmonary origin." (PMID 22078012, 2011). "The nuclei in the invasive tumour cells showed diffuse and strong positive immunoreactivity to TTF-1 marker." (PMID 20565809, 2010). "By immunocytochemistry performed on smears prepared from the pleural effusion sample, tumor cells were strongly immunoreactive for thyroid transcription factor-1 (TTF-1) and monoclonal CEA." (PMID 21167048, 2010). "In our case, all the tumor specimens (lung, pleura and breast) showed positive nuclear staining for TTF-1 and cytoplasmic staining for SP-A." (PMID 21167048, 2010). "The tumor cells demonstrated immunoreactivity for CD 15 (Leu-M1), TTF-1, Surfactant protein A (SP-A) and monoclonal CEA." (PMID 21167048, 2010). "Immunohistochemical examination revealed that the tumor cells were positive for thyroid transcription factor 1 (TTF-1), this tumor was diagnosed primary ACC of the lung." (PMID 20796281, 2010). "Potential correlations with age, sex, TNM-classification parameters and tumor grading as well as tumor transcription factor 1 (TTF1) and surfactant protein A (SPA) expression were investigated." (PMID 18700018, 2008). "A lung primary was unlikely as the tumour was characterized by positivity for cytokeratin 20 and negativity for the thyroid transcription factor-1 protein (TTF-1) in immunohistochemistry." (PMID 18667060, 2008). "Regarding CK20 and TTF1 expression in Capi3, some differences were recorded between the surgical tumor specimen and the corresponding xenograft." (PMID 18088404, 2007). "Previous studies suggested either a favourable or an unfavourable prognosis for patients with tumour showing a positive TTF1 staining." (PMID 16052216, 2005). "In univariate analysis, tumours differentiation and TTF1 staining significantly correlated with survival." (PMID 16052216, 2005). "Resected tumor from orthotopic model showed the expression of LUAD markers TTF-1 and CK7." (PMID 40275403, 2025). "However, the TTF‐1 positivity of the lung biopsy strongly suggests that the tumour was of lung origin." (PMID 41409415, 2025). "The tumor cells were strongly positive for markers associated with neuroendocrine differentiation (synaptophysin, chromogranin, CD56, and CAM 5.2) and, most notably, TTF-1, a nuclear marker highly suggestive of pulmonary origin." (PMID 40585617, 2025). "Univariate analysis did not identify a statistically significant relationship between DFS and variables including age, gender, smoking history, tumor localization, TTF-1, P40, chromogranin A, synaptophysin, adjuvant chemotherapy, adjuvant radiotherapy, or type of surgery." (PMID 41153253, 2025). "This favorable clinical behavior may be biologically explained by the role of TTF-1 in maintaining a more differentiated tumor phenotype and modulating key signaling pathways related to tumor proliferation and immune microenvironment interactions." (PMID 40647486, 2025).
tumor (continued). "Additionally, TTF-1 status negatively correlated with tumor volume (Spearman’s correlation coefficient = − 0.39) and Ki67 index (correlation coefficient = − 0.09), and positively with edema volume (correlation coefficient = 0.22)." (PMID 39630375, 2025). "In contrast, PD-L1 expression in tumor cells is often driven by intrinsic genetic alterations such as amplification, potentially explaining its lack of association with TTF-1." (PMID 40824335, 2025). "Classic adenocarcinoma (ADC) markers were used, including cytokeratin 7 (CK7), thyroid transcription factor 1 (TTF-1), and napsin A. The results of H&E staining and IHC indicated that the LCOs retained the histopathological characteristics of the original tumor tissue or malignant pleural effusion." (PMID 38773241, 2024). "Furthermore, TTF-1, a marker of thyroid differentiation, was generally negative, with only a few focally positive areas in the patient tumor sample and corresponding spheroids." (PMID 38500204, 2024). "In seven cases, TTF1 and p63 were coexpressed in the same tumor cells." (PMID 39584166, 2024). "Isolated from Sorbariasorbifolia, TTF1, also known as 5,2′,4′-Trihydroxy-6,7,5′-trimethoxyflavone, has showcased its capacity to inhibit tumor angiogenesis elicited by HepG-2 cells via reducing the VEGF, KDR, bFGF, COX-2, and HIF-1α levels of RNA and protein in key factors regulating angiogenesis." (PMID 38611849, 2024). "Immunohistochemically, the tumor cells were positive for cytokeratin, TTF-1, POU2F3, LCA, and CD43." (PMID 38649942, 2024). "Immunohistochemistry revealed that tumor cells were positive for TTF1 and TG." (PMID 38902753, 2024). "The tumor tissue of the patient we reported showed characteristic papillary structure and components of papillary epithelium under the microscope, and immunohistochemistry showed that the tumor cells expressed positive CK5/6, CK7, P63, and TTF1, which met the diagnostic criteria of MSGP." (PMID 39081690, 2024). "We further analysed the correlation between CXCL12, CD44v6, HIF1A, TGFBR2 and KRT7 expression in metastatic tumor tissues & exosomes with sex, age, habit, Tumor Differentiation grade, TNM stage, EGFR mutation status, AE1, Chromogranin, CDX2, CEA, CK20, TTF-1 & CK7." (PMID 38877052, 2024). "Surgical pathology of biopsy specimens revealed that duodenal lesions had tumor cells positive for thyroid transcription factor 1 (TTF-1) and focally positive for Napsin A, consistent with metastatic poorly differentiated adenocarcinoma from primary lung cancer." (PMID 39176211, 2024). "Use of novel immunohistochemistry markers like thyroid transcription factor-1 (TTF-1) may help diagnose the site of the primary tumour with accuracy in this clinical setting." (PMID 37273401, 2023). "In contrast, WFA-treated mice had reduced tumor burden with diminished TTF-1 and Ki67 expression." (PMID 37161053, 2023). "Moreover, the positive ratio of TTF-1 expression is closely related to the differentiation degree of ADC tumor tissue." (PMID 34631891, 2021). "TTF-1 expression status was also highly consistent between patient tumor and PDX." (PMID 33510214, 2021). "Carrizo and Luna described 2 pediatric cases, indicating that these tumors were similar to papillary thyroid carcinoma (PTC) for histological morphology; they documented the expression of thyroid transcription factor-1 (TTF-1) in tumor cell nuclei, and renamed them TL-LGNPPA." (PMID 34941144, 2021). "The remaining four (19.0%) cases also displayed weak TTF1 expression in 5–10% of the tumor cells." (PMID 34829389, 2021). "Likewise, previous reports along with these data show that reduced expression of TTF‐1 is significantly associated with unfavourable prognosis in patients with LAD, indicating a tumour suppressive function of NKX2‐1/TTF‐1 in lung tumourigenesis." (PMID 34014042, 2021). "In addition, NKX2‐1/TTF‐1‐regulated microRNA‐532‐5p has a tumour suppressive role by targeting KRAS in LADs." (PMID 34014042, 2021).
tumor (continued). "Furthermore, NKX2‐1/TTF‐1 shows different functions depending on cell conditions, being considered a double‐sword gene with lineage‐dependent tumour cell survival and tumour suppression activities depending on the context." (PMID 34014042, 2021). "Immunohistochemistrically, the tumour cells showed diffuse nuclear expression of TTF1." (PMID 32460843, 2020). "Immunohistochemical staining revealed the tumor cells to be positive for thyroglobulin and TTF-1." (PMID 32390944, 2020). "By immunohistochemistry, the tumor cells are positive for thyroglobulin and TTF1." (PMID 32632840, 2020). "We examined five cases in which > 1% of the tumor cells expressed p40 to determine whether p40‐positive tumor cells also expressed TTF‐1, neuroendocrine makers, or other SCC markers." (PMID 30957413, 2019). "There is quite a bit of evidence suggesting that TTF-1 plays paradoxical tumor-suppressive roles." (PMID 31196060, 2019). "In one case (case 5), p40‐positive tumor cells expressed TTF‐1, SYN, and CK5." (PMID 30957413, 2019). "The tumor cells in our case were positive for both TTF-1 and calcitonin." (PMID 30424779, 2018). "TTF-1, a classic marker for ADCs, was expressed in both tumor stages." (PMID 28419107, 2017). "The TG and TTF1 thyroid differentiation markers are expressed both in tumor and normal spheroids." (PMID 28039458, 2017). "A tumour evolution was strongly suggested by LT63, LT220 and LT268 behaviour in mouse, indeed in these models an epithelial to mesenchimal transition (EMT) was appreciable, with loss of TTF-1, acquisition of vimentin and Ki67 expression." (PMID 28751748, 2017). "TTF-1-mediated tumor differentiation is involved in the tumorigenesis of pulmonary adenocarcinoma." (PMID 29079814, 2017). "During carcinogenesis, EMT enables tumor cells to become invasive via downregulation of epithelial-specific marker, including E-cadherin, thyroid transcription factor 1 (TTF-1) and ZEB and upregulation of mesenchymal markers, including Vimentin, α-SMA, and N-cadherin." (PMID 29084594, 2017). "The entire tumor area and all of the follicles showed strong staining with the TTF-1 antibody." (PMID 27409604, 2016). "Thus, we used immunocytochemistry with cancer-specific markers in effusions such as TTF-1 or the epithelial marker EpCAM combined with the mesothelial marker calretinin to better quantify tumor cells across passages." (PMID 27548442, 2016). "Moreover, the tumor cells lack immunoreactivity for the thyroid-specific markers TG, TTF-1, and TPO." (PMID 27082575, 2016). "Out of 2,450 diagnostic samples (containing >10 % of tumor cells), the occurrence of EGFR gene mutations was 9 %; more frequently in women (13.9 %) and adenocarcinoma patients (10 %), particularly with accompanying expression of TTF1 (13.0 %)." (PMID 25086987, 2015). "However, the first two tumours are generally differentiated by their positivity to TTF-1 (thyroid transcription factor-1), and the latter by the presence of focal granular necrosis and haemorrhage within the lesion, and its prominent vascularity." (PMID 25815059, 2015). "TTF-1 is used as a marker to determine the origin of another tumour from lung or thyroid." (PMID 26438229, 2015). "In this study, we examined whether SCLC is really a central-type tumor and the relationship between tumor location, TTF-1 expression and prognosis of SCLC." (PMID 26705222, 2015). "The frequency of TTF-1 immunoreactivity in extrapulmonary adenocarcinomas, except the thyroid, is lower than 1 %, and the positivity for TTF-1 may be interpreted as a definite evidence that the tumour originates from the lung." (PMID 26438229, 2015). "The tumour cells in the present case were immunoreactive to calcitonin, TTF-1, and thyroglobulin." (PMID 25478248, 2014). "TTF1 expression was co-related with high tumor grade, lymph node metastasis and vascular invasion." (PMID 24581278, 2014).
tumor (continued). "In NKX2-1 negative mice models with KRAS mutations, reduced tumor volume was seen when TTF-1 expression was induced." (PMID 25594059, 2014). "TTF-1, Bcl-2, and ERCC1 were closely associated with tumor stage (P < 0.05)." (PMID 24667263, 2014). "Whether TTF-1 itself has a tumor suppressor or tumor-promoting function awaits further clarification." (PMID 25594059, 2014). "This lesion shared the papillary pattern of the primary tumor and was TTF-1-positive." (PMID 24944657, 2014). "Mucus gland adenoma is an extremely rare benign lung tumor, presumed to arise from the bronchial mucus glands; it is a TTF-1 negative tumor, centrally located, causing the clinical manifestations of obstruction." (PMID 23533890, 2013). "Another very important tumor marker is thyroid transcription factor-1 (TTF-1)." (PMID 23691324, 2013). "Tumour cells expressed the thyroid transcription factor 1 (TTF-1) antigen." (PMID 21320334, 2011). "In SMP component, positive and negative tumor cells for thyroid transcription factor-1 (TTF-1) and surfactant protein A (SP-A) staining were observed in the case 1, on the other hand, the case 2 showed TTF-1 expression and SP-A repression in almost all tumor cells." (PMID 21955603, 2011). "Tumor cells outside SMP in case 1 showed strong TTF-1 expression." (PMID 21955603, 2011). "Positive staining for TTF-1 should be factored into each clinical setting when determining whether the tumor is an EPSCC or a metastatic lesion." (PMID 18817561, 2008). "Indeed in these areas one observes a modified NIS, Tg, and TTF-1 immunolabelling and high proliferation indices, as in human aggressive tumours." (PMID 18985036, 2008). "Recently, CD56 (neuronal cell adhesion molecule) and TTF-1 (Thyroid Transcriptional Factor-1) were also reported to be high positivity in small cell carcinoma arising in different organs and thought to be useful markers for diagnosis of the tumor." (PMID 17335582, 2007). "Tumours expressing positive TTF1 staining were associated neither with demographics (i.e. gender and age) nor with disease characteristics (i.e. PS, TNM stage or presence of metastasis)." (PMID 16052216, 2005). "The authors suggested that PPETS could represent the sellar/intracranial equivalent of low‐grade nasopharyngeal papillary adenocarcinoma, a slow‐growing tumor, typically cured by surgical excision, also characterized by a similar morphology and immunophenotype, showing diffuse TTF‐1 positivity." (PMID 39350562, 2025). "Conversely, volumetric analysis demonstrated superior diagnostic efficacy in discriminating Ki-67 and TTF-1 expression, potentially due to the fact that the two-dimensional region of interest may not reflect the tumor heterogeneity comprehensively." (PMID 39456114, 2024). "In addition, TTF-1 immunostaining in tumor tissue may be useful as a predictive factor for the efficacy of regimens combined with PEM." (PMID 36614938, 2022). "The expression patterns of TTF-1 from IHC double-stained sections were also taken as references to exclude errors that could be caused by mistaking non-tumor cells for tumor cells." (PMID 32321471, 2020). "Therefore, tumor location and TTF-1 expression could predict expression status of PD-L1, and could potentially serve as clinical response to immunotherapy." (PMID 33585516, 2020). "In particular, it was observed a significant over-expression (p < 0.05) of TTF1 in four samples, two samples showed a significantly lower expression (p < 0.05), and one sample showed no variation, in comparison with normal thyroid tissue from regions, adjacent to the tumor area, used as control." (PMID 29561759, 2018). "In this study, to address these questions, we examined whether SCLC was really a central-type tumor and whether tumor location and TTF-1 expression have prognostic relevance, using thin-sliced chest CT images, TTF-1 expression data, and clinicopathological data including prognosis." (PMID 26705222, 2015).